TMPOP2 (thymopoietin pseudogene 2)
Synonyms: lncRNA-EBIC
Gene: Processed pseudogene on chromosome 16 (74,667,506 to 74,668,706, forward strand). Ensembl gene ENSG00000262904.
Diseases named in the same sentence as TMPOP2 in open-access papers:
TMPOP2 is named in the same sentence as 1 disease in open-access papers, as found by Europe PMC text mining. Sharing a sentence is not in itself a finding about the gene and the disease. The quoted sentences say what the papers report.
cervical cancer (5 papers, 2020 to 2022). A primary or metastatic malignant neoplasm involving the cervix. "Another lncRNA that was upregulated in cervical cancers is thymopoietin pseudogene 2 (TMPOP2) lncRNA." (PMID 34361112, 2021). "Expression of thymopoietin pseudogene 2 (TMPOP2) was found to be upregulated in an oncoprotein-dependent manner in HPV+ cervical cancer cells as well as in HPV16 E6/E7 expressing keratinocytes." (PMID 33427604, 2021). "The EZH2-Binding lncRNA in cervical cancer, EBIC, (also known as thymopoietin pseudogene 2, TMPOP2), may promote motility and invasion of cervical cancer cells by repressing CDH1 (E-Cadherin) expression though EZH2." (PMID 32326624, 2020). "LncRNA-EBIC -In cervical cancer cells, the expression of E6 and E7 stimulates the expression of EZH2-binding lncRNA (lncRNA-EBIC), also known as TMPOP2 (Thymopoietin pseudogene 2)." (PMID 35774512, 2022).